CTLA4 (cytotoxic T-lymphocyte associated protein 4)
Diseases named in the same sentence as CTLA4 in open-access papers (continued):
Sharing a sentence is not in itself a finding about the gene and the disease.
hypophysitis (201 papers, 2014 to 2026). Inflammation of the pituitary gland. "Thyroid dysfunctions are the most frequent events, whereas hypophysitis and adrenal insufficiency occur less often and are strongly associated with anti–CTLA-4 therapy." (PMID 41301042, 2025). "Hypophysitis associated with anti-CTLA4 antibodies and anti-PD1/PDL1 antibodies exhibits distinct clinical and pathological characteristics." (PMID 39941803, 2025). "Combinations that involve anti-CTLA-4 drugs, for instance, are especially likely to cause hypophysitis because CTLA-4 is expressed in the cells of the pituitary gland, leading to potentially permanent damage to the glands if it is not immediately identified." (PMID 40700298, 2025). "Hypophysitis associated with ipilimumab, or CTLA-4 combination therapy, tended to be more severe and occurred earlier compared to that associated with PD-1/PD-L1 inhibitors." (PMID 41510421, 2025). "CTLA-4 inhibitors like ipilimumab are more commonly associated with hypophysitis and subsequent adrenal insufficiency, leading to cortisol deficiency and impaired water excretion." (PMID 40361386, 2025). "Hypophysitis is most frequently associated with CTLA-4 inhibitors, either alone or in combination with PD-1/PD-L1 blockade." (PMID 40867279, 2025). "There were a total of 18 papers, including 1,823 patients who were treated with CTLA-4 agents, out of which 699 were analysed for CTLA-4-associated hypophysitis." (PMID 41510421, 2025). "Endocrine irAEs associated with anti-PD-1 therapies predominantly included thyroid disorders, while hypophysitis was more frequently linked to anti-CTLA-4 agents." (PMID 41301042, 2025). "Hypophysitis, or inflammation of the pituitary gland, is one of the most common ICPi-related endocrinopathies and is mainly associated with anti-CTLA-4 therapy, but can also be encountered with PD1 and PDL-1 or combination therapies." (PMID 41510421, 2025). "Hypophysitis was strongly associated with CTLA-4 inhibitors, reported in 10–68% of treated patients vs. 2–8% in the PD-1/PD-L1 cohorts." (PMID 41301042, 2025). "CTLA-4-induced hypophysitis shows ACTH deficiency in 95%, central hypothyroidism in 85%, and hypogonadism in 75% of cases." (PMID 40860571, 2025). "Immune checkpoint inhibitors (ICIs), particularly anti-CTLA-4 agents or combined CTLA-4/PD-1 regimens, are associated with an increased risk of hypophysitis, occurring in approximately 3–14% of treated patients." (PMID 40867279, 2025). "Anti-CTLA-4 monotherapy exhibited a higher association with hypophysitis (leading to hypopituitarism) and adrenal insufficiency, while anti-PD-1/PD-L1 monotherapy was found to be predominantly linked to thyroid dysfunction and type 1 diabetes mellitus." (PMID 38539511, 2024). "Secondary AI can be caused by hypophysitis, which is most often induced by the CTLA-4 inhibitor ipilimumab, with a prevalence of 1.8–17%." (PMID 38915406, 2024). "Previous reports indicate that the duration before the onset of hypophysitis and thyrotoxicosis caused by a combination of anti-PD-1 and anti-CTLA-4 antibodies differs, averaging 10.3 weeks and two weeks after the first administration, respectively." (PMID 38910605, 2024). "In our study, only two patients with ICI-associated hypophysitis presented with headache, multiple anterior pituitary hormone deficiencies and abnormalities on imaging, both of which had received anti-CTLA-4 inhibitors as combination therapy." (PMID 38681767, 2024). "Immune-related hypophysitis is most frequently associated with the CTLA-4 inhibitor ipilimumab and although hypophysitis has also been reported in patients receiving anti-PD1/PD-L1 therapy, this occurs with a much lower incidence." (PMID 38681767, 2024). "Two patients presented with headache accompanied by changes consistent with hypophysitis on imaging and multiple pituitary hormone deficiencies both of which received combination anti-PD-1 and CTLA4 inhibitor therapy (nivolumab plus ipilimumab)." (PMID 38681767, 2024).
hypophysitis (continued). "Immunotherapy-related hypophysis is emerging as an important cause of hypopituitarism in cancer patients treated with cytotoxic T-lymphocyte associated protein 4 (CTLA-4) or programmed cell death protein 1 (PD-1) inhibitors." (PMID 39370498, 2024). "In particular, a Japanese study showed that HLACw12 and HLA-DR15 were significantly associated with anti-CTLA-4 related hypophysitis, whereas HLA-DQB106:01, HLA-DPB109:01, and HLA-DRB5*01:02 were significantly associated with anti-PD-1-related hypophysitis." (PMID 37623461, 2023). "Patients on CTLA-4-based therapy have a specific risk of developing hypophysitis and should be monitored with routine fasting serum cortisone levels and standardized symptom questionnaires for irAE screening." (PMID 37271776, 2023). "In previous reports, abnormalities in pituitary MRI are present in 81% of cases due to anti-CTLA-4, while in 18% of patients with hypophysitis caused by anti-PD-1/PD-L1, the initial enlargement of pituitary tends to resolve within weeks." (PMID 37415148, 2023). "We were able to confirm that hypophysitis is more likely to be associated with CTLA-4-inihibitor therapy, which is consistent with the literature." (PMID 37271776, 2023). "Lastly, the prevalence of hypophysitis in patients treated with anti-PD-1 and anti-PD-L1 increases when these ICIs are associated with anti-CTLA-4 antibodies or when patients have pre-existing autoimmune or inflammatory disorders." (PMID 37623461, 2023). "For example, the ectopic expression of CTLA-4 in pituitary gland cells has been related to a higher risk of developing hypophysitis during ipilimumab treatment." (PMID 37511260, 2023). "The increased incidence of hypophysitis in patients treated with anti-CTLA-4 has also been linked to the potential ectopic expression of CTLA-4 at the pituitary gland level." (PMID 37623461, 2023). "Supporting this model, PD-1/PD-L1 therapies are more often associated with development of thyroiditis, while anti-CTLA-4 antibody therapy is more frequently associated with hypophysitis." (PMID 37168978, 2023). "We assume that the risk of hypophysitis is the result of toxicity due to treatment with CTLA-4 inhibitor, and we represent the level of toxicity by the concentration of TNF-α in the tumor." (PMID 36355837, 2022). "The incidence of ICI-associated hypophysitis varies depending on the agents used—incidences of up to 13% have been reported with CTLA-4 therapy but only up to 3% with PD-1/PD-L1 therapy." (PMID 35877230, 2022). "In anti-CTLA-4-induced hypophysitis, ACTH deficiency is most common (95%) and is often accompanied by other pituitary insufficiencies." (PMID 36149449, 2022). "The most frequent irAEs associated with anti-PD-1 monoclonal antibody (mAb) treatment are thyroid dysfunctions, while hypophysis is mostly linked to anti-CTLA-4 treatment." (PMID 36276090, 2022). "When compared to PD-1 and PD-L1 inhibitors, CTLA4 inhibitors are more likely to cause colitis, hypophysitis, and dermatitis, while pneumonitis, hypothyroidism, and skeletal symptoms (myalgias, arthralgias) are less frequent." (PMID 36140517, 2022). "Hypophysitis is mainly associated with anti-CTLA4 mAbs (3.9–8.1%), whereas thyroid dysfunction is predominantly associated with anti-PD-1/PD-L1 mAbs (6.4–9.8%)." (PMID 35158860, 2022). "There are key distinctions in the clinical phenotype between hypophysitis caused by CTLA-4 compared with PD-1 inhibitors." (PMID 35912205, 2022). "Overexpression of pituitary CTLA-4 was reported in a patient with severe ipilimumab-associated hypophysitis." (PMID 35432346, 2022). "CTLA-4 inhibitors are commonly associated with enteritis, hypophysis, and skin rashes whereas PD-1 inhibitors can cause immune pneumonia, muscle and joint pain, and hypothyroidism." (PMID 36187930, 2022). "Anti-CTLA-4-induced hypophysitis often leads to pan-hypopituitarism and is associated with mild pituitary enlargement." (PMID 35205804, 2022).
hypophysitis (continued). "It has been suggested that hypophysitis is caused by complement activation from endogenous autoantibodies and/or exogenous IgG1 anti-CTLA-4 (ipilimumab)." (PMID 35432346, 2022). "Hypophysitis is rare during nivolumab treatment (0.1–0.6%); it is particularly associated with anti-cytotoxic T-lymphocyte-associated protein 4 (anti-CTLA-4) therapy." (PMID 34587185, 2021). "It is thus common to find autoantibodies in the mouse models of anti–CTLA-4–induced irAES, in particular anti-pituitary antibodies associated with hypophysitis development, which is a frequent adverse event observed in patients treated with ipilimumab." (PMID 35126126, 2021). "Anti-PD1, anti-CTLA4, and their combinations can cause hypophysitis, but with different frequencies." (PMID 34597942, 2021). "PD1/PDL1 inhibitor-induced hypophysitis is a clinical entity different from those associated to cytotoxic T-lymphocyte antigen-4 (CTLA4) inhibitors, with less obvious clinical and radiological signs, and probably a different mechanism." (PMID 33066179, 2020). "Secondary adrenal insufficiency in the course of hypophysitis (with a higher risk in the course of CTLA-4 inhibitor treatment) or due to metastatic lesions in the pituitary have to be taken into consideration." (PMID 32824462, 2020). "The risk of hypophysitis is significantly lower in nivolumab therapy in comparison to anti-CTLA-4 treatment." (PMID 32824462, 2020). "PD1/PDL1 inhibitor induced-hypophysitis seems to be a clinical entity different from those associated to CTLA4 inhibitors, with less obvious clinical and radiological signs, and probably a different mechanism." (PMID 33066179, 2020). "Increased risk of ADR reporting emerged in anti-CTLA-4 (e.g., hypophysitis/hypopituitarism, adrenal insufficiency) or in anti-PD-1/PD-L1 (e.g., thyroid dysfunction, T1DM, fulminant T1DM)." (PMID 32507965, 2020). "Combination therapy, mostly the association of PD1 and CTLA4 inhibitors, has been associated with the most frequent occurrence of hypophysitis, ranging from 8.8 to 10.5%." (PMID 33066179, 2020). "Thyroid disorders (TDs), typically associated with anti-PD-1 antibodies and hypophysitis (IH) commonly related to anti-CTLA-4 therapy, are the most frequent endocrine toxicities." (PMID 33064663, 2020). "We found anti-CTLA-4 mAb to be the ICI most frequently associated with hypophysitis and anterior pituitary hormone(s) deficiencies (n = 188 as monotherapy) compared with Anti-PD-1 mAbs (n = 13)." (PMID 30693099, 2019). "Recent research on anti-CTLA-4 associated hypophysitis suggests that local expression of CTLA-4 in the pituitary leads to antibody binding and activation of the complement pathway with subsequent site-specific inflammation and tissue injury." (PMID 28031819, 2016). "Immunotherapy-associated hypophysitis occurs in up to 10–15 % of patients receiving agents targeting CTLA-4, on average 2–3 months after starting therapy." (PMID 28702249, 2016). "Anti PD-1 or anti PD-L1 monotherapy causes hypophysitis less frequently than anti-CTLA-4 therapies." (PMID 39941803, 2025). "Testing of pituitary hormones including a morning ACTH, luteinization hormone, FSH, estradiol (premenopausal females), testosterone (males), and prolactin is recommended when there an increased risk of hypophysitis, especially when CTLA-4 and PD-1 inhibitors are combined." (PMID 41140515, 2025). "For anti-CTLA-4 inhibitors, higher doses are associated with a higher incidence of hypophysitis." (PMID 41373773, 2025). "Treatment: In CTLA-4-associated hypophysitis, reported in 17 out of 18 studies, high-dose glucocorticoids such as dexamethasone or prednisolone at 1 mg/kg for approximately two weeks are commonly administered, followed by a tapering regimen to reach a physiological maintenance dose." (PMID 41510421, 2025).
hypophysitis (continued). "Notably, hypophysitis is more commonly linked to cytotoxic T-lymphocyte-associated protein 4 (CTLA-4) inhibitors, with an incidence of approximately 10%, whereas PD-1 inhibitors like pembrolizumab have a reported incidence of less than 1%." (PMID 40416222, 2025). "ICI class-specific differences are also evident on pituitary MRI, with CTLA-4 inhibitor-associated hypophysitis more commonly being associated with pituitary enlargement, homogeneous enhancement, and stalk thickening, whereas PD-1/PD-L1 inhibitors rarely demonstrate radiologic pituitary changes." (PMID 41002414, 2025). "Anti-cytotoxic T-lymphocyte antigen-4 (CTLA-4) agents are associated with the risk of adrenal insufficiency and hypophysis, whereas anti-programmed death-1 (PD-1)/programmed death ligand-1 (PD-L1) therapy is closely associated with insulin-dependent DM and thyroid dysfunction." (PMID 39450164, 2024). "The difference in recovery rate of TSH deficiency between the studies might be explained by a more severe TSH deficiency in patients with anti-CTLA-4 induced hypophysitis; 57 of 62 patients in the study of Nguyen were treated with anti-CTLA-4 therapy." (PMID 39135626, 2024). "Compared with IAD, the anti-CTLA-4 antibody is more likely to cause hypophysitis." (PMID 38318292, 2024). "Interestingly, in cases of combined CTLA-4 and PD-1 blockade, the associated risk of hypophysitis, as well as thyroid dysfunction, was higher." (PMID 38539511, 2024). "Animal studies have found the pituitary gland expresses CTLA-4 in a subset of cells, which are targets for CTLA-4 antibody binding and this may explain the predisposition towards hypophysitis with anti-CTLA-4 therapy." (PMID 38681767, 2024). "Anti-CTLA-4 was associated with statistically significant increased odds of hypophysitis compared with conventional therapy (OR 60.96, 95% CrI 15.88 to 374.52), anti-CTLA-4 plus conventional therapy (OR 15.49, 95% CrI 1.96 to 142.73), and anti-PD-1/PD-L1 (OR 4.81, 95% CrI 2.31 to 11.59)." (PMID 38372756, 2024). "Patients receiving CTLA-4 inhibitors have a higher risk of developing hypophysitis, while those receiving PD-1/PD-L1 inhibitors possess a higher risk of primary thyroid dysfunction and, rarely, type 1 diabetes mellitus, central diabetic insipidus, and hypoparathyroidism." (PMID 36358624, 2022). "Hypophysitis is mostly linked to anti-CTLA-4 treatment, diarrhea, colitis and liver dysfunction." (PMID 36276090, 2022). "Indeed, the combination of anti-CTLA4 and anti-PD-1 mAbs is associated with a higher incidence of endocrinopathies (hypothyroidism: 10.2–16.4%; hyperthyroidism: 9.4–10.4%; hypophysitis: 8.8–10.5%) than the individual use." (PMID 35158860, 2022). "Clinically, most cases may be classified in three different nosocomial entities: hypophysitis, mostly associated with anti-CTLA4 antibodies, thyroid dysfunction, more related to anti-PD1 CPIs and insulin-deficient diabetes mellitus." (PMID 35631383, 2022). "In order to reduce the risk of hypophysitis and other severe adverse events, steroids may be combined with CTLA-4 inhibitor; they reduce toxicity, but they also diminish the anti-cancer effect of the immunotherapy." (PMID 36355837, 2022). "ICI-induced hypophysitis is also different when caused by CTLA-4 blockade or PD-1/PD-L1 blockade." (PMID 35205804, 2022). "Increasing evidence suggests hypophysitis may be associated with immunotherapy (interleukin 2, interferon) and medications targeting cytotoxic T-lymphocyte antigen-4 (CTLA-4) or programmed cell death 1 (PD-1)." (PMID 34544399, 2021). "Interestingly, hypophysitis appears to be more common after use of another checkpoint inhibitor, ipilimumab (an antibody against cytotoxic T- lymphocyte–associated antigen 4 [CTLA-4]), alone or in combination with nivolumab." (PMID 34544399, 2021).
hypophysitis (continued). "ICPI-related hypophysitis is frequently (up to 17% of cases) associated with ipilimumab, an anti-cytotoxic T lymphocyte-associated antigen-4 (CTLA-4) antibody, but hypophysitis is an extremely rare event (< 1%) in patients treated with other ICPIs, such as nivolumab." (PMID 33892782, 2021). "However, the prevalence of hypophysitis in patients treated with anti-PD-1 and anti-PD-L1 increases when these ICIs are associated with anti-CTLA-4 antibodies or when patients have pre-existing autoimmune or inflammatory disorders." (PMID 34439190, 2021). "Secretion of thyroid-stimulating hormone (TSH) and luteinizing hormone (LH)/follicle-stimulating hormone (FSH) is frequently impaired in the hypophysitis associated with CTLA-4 inhibitor therapy, along with impairment in adrenocorticotropic hormone (ACTH) secretion." (PMID 33977343, 2021). "It is reported that hypophysitis is particularly associated with anti-CTLA-4 therapy." (PMID 31694698, 2019). "Hypophysitis is more commonly associated with cytotoxic T-lymphocyte-associated protein 4 (CTLA-4) inhibitors, such as ipilimumab, whereas thyroid disorders are more common in patients receiving antibodies against programmed cell death-1 receptor (anti-PD-1) such as Pembrolizumab and Nivolumab." (PMID 31807385, 2019). "Pituitary CTLA-4 expression levels appear to vary widely and may affect the risk of developing hypophysitis following treatment with Ipilimumab." (PMID 28702249, 2016). "Older age and male gender may be risk factors for the development of hypophysitis with anti-CTLA-4 medications." (PMID 28702249, 2016). "Moreover, hypophysitis associated with anti-CTLA-4 antibodies tends to occur earlier." (PMID 41573497, 2025). "Indeed, the combination of anti-CTLA4 and anti-PD-1 mAbs is associated with a higher incidence of endocrinopathies (hypothyroidism: 10.2–16.4%; hyperthyroidism: 9.4–10.4%; hypophysitis: 8.8–10.5%; primary adrenal insufficiency: 5.2–7.6%) than the individual use." (PMID 35311088, 2022). "CTLA-4 genotyping might help stratify patients undergoing immunotherapy not only in terms of their response to therapy but also the risk of developing irAEs, including hypophysitis." (PMID 34682890, 2021). "CTLA-4 inhibitor-induced hypophysitis affects several hormonal axes, occurs earlier in the course of treatment, and is dose-dependent." (PMID 41002414, 2025). "Pituitary autoantibodies targeting thyrotrophs, corticotrophs, and gonadotrophs have been detected in patients treated with anti-CTLA-4 antibodies (e.g., ipilimumab) who subsequently developed hypophysitis." (PMID 39941803, 2025). "According to a recent meta-analysis, the incidence of hypophysitis is <0.1% with anti-PD-L1 antibodies, 0.4% with anti-PD-1 antibodies, 3.2% with anti-CTLA-4 antibodies, and 6.4% with combination therapy." (PMID 41573497, 2025). "Hypophysitis induced by CTLA-4 inhibitors, particularly ipilimumab and CTLA-4-based combination therapies, were more commonly associated with hypopituitarism." (PMID 41510421, 2025). "Hypophysitis, most seen with anti-CTLA-4 therapy, is thought to result from a combination of type II hypersensitivity reactions involving IgG or IgM antibodies and T cell-mediated type IV hypersensitivity." (PMID 39859105, 2025). "In the CTLA-4 group, all 699 patients underwent MRI [6 to 23], out of which 235 had radiological evidence of hypophysitis." (PMID 41510421, 2025). "Immune checkpoint inhibitors (e.g., combined anti-CTLA-4 and anti-PD-1 therapy) have been linked to transient CAI due to hypophysitis, with recovery following treatment cessation." (PMID 41446490, 2025). "CTLA-4 inhibitors (ipilimumab, tremelimumab) were characterized by a high frequency of hypophysitis, reported in 25–38% of cases, often appearing later (15–20 weeks after treatment initiation)." (PMID 41301042, 2025). "In the CTLA-4 group, patients received ipilimumab for 2-12 cycles (mean: 3.3) before hypophysitis onset." (PMID 41510421, 2025).